ATF3 (activating transcription factor 3)
Diseases named in the same sentence as ATF3 in open-access papers (continued):
Sharing a sentence is not in itself a finding about the gene and the disease.
ZIKV infection (continued). "Therefore, ATF3 and ATF4 have opposing roles that together modulate the cellular response to ZIKV infection." (PMID 39212382, 2024). "By immunoblot, the protein levels of STAT1 in ATF3 KO cells, without and with ZIKV infection, were notably decreased compared to WT cells." (PMID 39212382, 2024). "We recently determined that ATF3 is activated by ATF4, the master regulator of the integrated stress response, and functions to promote the expression of select immune response genes to restrict ZIKV infection." (PMID 39065267, 2024). "ATF3 transcription was slightly, but not significantly, upregulated following ZIKV infection in WT cells but transcription was significantly reduced in the EGR1 null-infected cells." (PMID 35746681, 2022). "We previously showed that ATF3 was upregulated during ZIKV infection of SH-SY5Y cells and PMBC isolated from early acute ZIKV-infected patients; however, the upstream effector proteins inducing ATF3 expression and the impact of ATF3 activation on ZIKV gene expression were unknown." (PMID 39212382, 2024). "In addition, the lack of a cytopathic effect could be due to the induction of the pro-survival genes during the ZIKV infection of hBMECs, including EGR1, ATF3, and BIRC3." (PMID 36557673, 2022). "This study noted the induction of ATF3, EGR1, JUNB, IRF7, ISG15, HERC5/6, additional ISGs, chemokines CCL5 and CXCL10, prosurvival responses, and decreased proapoptotic genes, similar to gene induction levels we found to be induced by ZIKV infection of hBMECs (GEO GSE98889)." (PMID 28698279, 2017). "Unexpectedly, however, ATF3 protein, but not the mRNA, levels dramatically increased following inhibition of the ISR and ZIKV infection." (PMID 39212382, 2024). "When we inhibited the ISR pathway during ZIKV infection using ISRIB, a broad ISR inhibitor, or GSK2606414, a PERK inhibitor (data not shown), ATF4 protein expression was reduced, and ATF3 mRNA levels were negligible (and data not shown)." (PMID 39212382, 2024). "From our RNA-seq data, the absence of ATF3 specifically led to a decrease in the transcription of genes involved in IFN pathways, which supports the role of ATF3 as a positive transcriptional regulator of these genes during ZIKV infection." (PMID 39212382, 2024).
Cerebral ischemia (6 papers, 2022 to 2026). Restriction of arterial blood supply to the brain associated with insufficient oxygenation to support the metabolic requirements of the tissue. "Our findings suggested that ATF3 repressed neuronal apoptosis and microglia activation caused by cerebral ischemia via targeting CCL2 and mediating the TLR4/NF‐κB signaling." (PMID 35263513, 2022). "Additionally, the increase of ATF3 after brain ischemia is associated with reduction of neuronal death and more efficient synaptic recovery." (PMID 37237015, 2023). "For instance, FTO inhibits oxidative stress by regulating Nrf2 expression in models of cerebral ischemia/reperfusion injury and modulates neuronal oxidative stress through ATF3 regulation in an m6A-dependent manner." (PMID 41602161, 2026). "ATF3 also inhibits the apoptosis of neurons and activation of microglia in the rat model of cerebral ischemia and alleviates ABI in rats." (PMID 37033632, 2023). "Recently, using gene ontology (GO) enrichment and KEGG pathway approaches, it was suggested that ATF3 via targeting CCL2-mediated TLR4/NF-κB signaling repressed microglia activation upon cerebral ischemia." (PMID 36768628, 2023). "For the ATF3 underexpression approach, ATF3 KO mice (a generous gift from Dr. Tsonwin Hai at Ohio State University) were used to test the role of ATF3 on cerebral ischemia." (PMID 36768628, 2023). "Their potential involvement into recovery after brain ischemia was claimed on the finding that they are co-expressed with beneficial ATF3." (PMID 37237015, 2023). "ATF3 exerted a critical role in regulation of caspase-dependent neuronal apoptosis signaling in focal cerebral ischemia-reperfusion injury." (PMID 36219954, 2022). "The rats with cerebral ischemia exhibited a certain weight gain after ATF3 overexpression treatment compared with MCAO‐treated rats, while the body weight of MCAO rats was downregulated again after CCL2 overexpression." (PMID 35263513, 2022). "Cerebral ischemia results in neuronal death hours to days after reperfusion of the blood supply, and artificial overexpression of ATF3 principally protected cultured neurons against glutamate cytotoxicity." (PMID 35263513, 2022). "Previous study reported that ATF3 is significantly overexpressed in brain ischemia from GSE22255 microarray dataset." (PMID 36219954, 2022). "Interestingly, however, another study reports opposite results, whereby after ATF3 gene knockout, the infarct size increased significantly in the mouse model of cerebral ischemia." (PMID 37033632, 2023). "Despite the substantial over-expression of both ATF3 and HDAC2 after brain ischemia, only the increase in ATF3 and BCL11B co-expression was observed, while BCL11B and HDAC2 co-expression was not altered, indicating increase of BCL11B was associated with the beneficial processes after brain ischemia." (PMID 37237015, 2023). "However, the precise mechanism of ATF3 in cerebral ischemia is little known so far." (PMID 35263513, 2022). "Therefore, we wonder whether ATF3 could also regulate the transcription of a gene to participate in cerebral ischemia." (PMID 35263513, 2022). "Before quantifying the merged signal, integrated optical density for ATF3 and HDAC2 was measured to confirm their over-expression after brain ischemia." (PMID 37237015, 2023). "The results demonstrated that ATF3 protein was significantly reduced and CCL2 protein was significantly increased in rats with cerebral ischemia, while TLR4/NF‐κB signaling pathway was significantly activated in MCAO rats." (PMID 35263513, 2022).
head and neck squamous cell carcinoma (6 papers, 2013 to 2025). A squamous cell carcinoma that arises from any of the following anatomic sites: lip and oral cavity, nasal cavity, paranasal sinuses, pharynx, larynx, and salivary glands. "That suggestion was supported by another study in which cisplatin-induced ATF3 in head and neck squamous cell carcinoma cells resulted in induction of apoptosis accompanied by an increased level of PMAIP1 through cooperative binding of ATF3 and ATF4 to the PMAIP1 promoter." (PMID 31296259, 2019). "Consistent with persister enrichment in ICB treated tumors, ATF3 and IDO1 are induced in 4MOSC159 orthotopic syngeneic mouse head and neck squamous cell carcinoma tumors which have regressed during anti-PD-1 treatment." (PMID 40166148, 2025). "Furthermore, the ERAD-mediated ATF3/ATF4 complex binds to the NOXA promoter region to regulate NOXA transcription in mantle cell lymphoma and head and neck squamous cell carcinoma cells." (PMID 38039297, 2023). "ATF3/4 was found to induce NOXA expression by binding to NOXA promoter in head and neck squamous cell carcinoma (HNSCC) in response to cisplatin treatment." (PMID 35454137, 2022).
Hypertension (6 papers, 2015 to 2025). The presence of chronic increased pressure in the systemic arterial system. "ATF3 was increased in carotid artery of hypertensive rats, and downregulation of ATF3 was associated with the protective effect of enalapril against hypertension." (PMID 36704356, 2022). "There were several genes affected by high-intensity interval training during HFD hypertension, which were Trim39, Nr4a1, Plekhf1, Tgm2, Lgals1, Egr1, and Atf3." (PMID 41516177, 2025). "In summary, our data revealed that pathological mechanical stretch suppresses the expression of ACE2 via the p38 MAPK/ATF3 pathway and post-transcriptional regulation by miR-421, contributing to promote VSMC dysfunction and vascular remodeling in the hypertension process." (PMID 33536929, 2020).
myocardial infarction (6 papers, 2020 to 2024). Gross necrosis of the myocardium, as a result of interruption of the blood supply to the area, as in coronary thrombosis. "Our research delves into the crucial topic of the ferroptosis pathway genes and the pivotal role of ferroptosis regulator ATF3 in myocardial infarction." (PMID 39070785, 2024). "The Rrad protein product, RAD-GTPase, is a well-characterized L-type calcium channel inhibitor, and its up-regulation has been described in human myocardial infarction under the control of the AP-1 family transcription factor ATF3." (PMID 39383190, 2024). "Myocardial infarction is closely associated with hypoxia-related genes such as SELP, CXCL2, MyD88, and S100a8 and genes related to Atf3, PTGS2, Cxcl1, and Socs3 ferroptosis." (PMID 37181809, 2023). "A recent bioinformatics study on acute myocardial infarction (AMI) demonstrated that ATF3 was a key transcription factor in the immune response to AMI." (PMID 33679395, 2021). "In conclusion, ATF3 may involved but partially regulates ferroptosis pathway genes in myocardial infarction." (PMID 39070785, 2024). "In the heart of myocardial infarction, the ferroptosis pathway is elevated in cardiomyocytes and adipocytes injury-related cardiac regions (border zone, ischemic zone, and fibrotic zone), as well as the ATF3." (PMID 39070785, 2024). "The gene ATF3 (Activating Transcription Factor 3) has been upregulated in cardiomyocyte subtypes activated by myocardial infarction (MI) stimulation." (PMID 39070785, 2024). "The expression of ATF3, ferroptosis pathway geneset (FPG), and geneset of potential regulators for ATF3 (GPRA, predicted by the PROMO database) was explored in the public human myocardial infarction single-cell RNA-seq (sma) dataset." (PMID 39070785, 2024).
renal carcinoma (6 papers, 2014 to 2025). A carcinoma arising from the epithelium of the renal parenchyma or the renal pelvis. "Our study supports ATF3 as a tumor suppressor in RCC that restrains renal cancer cell proliferation." (PMID 38586033, 2024). "In summary, our findings demonstrate that FADS1 inhibition effectively curtails renal cancer cell proliferation in vitro as well as tumor formation in vivo, primarily through the activation of the ATF3 axis-mediated ER stress." (PMID 38586033, 2024). "Taken together, the inhibition of FADS1 in renal cancer cells promoted ER stress via activating the PERK/eIF2α/ATF4 pathway, with ATF3 likely playing a key role in mediating this effect." (PMID 40121894, 2025). "Taken together, inhibition of FADS1 in renal cancer cells promoted ER stress, with the likelihood that the ATF family of genes, especially ATF3, plays a key role in mediating this effect." (PMID 38586033, 2024).
acute myeloid leukemia (5 papers, 2015 to 2025). Acute myeloid leukemia (AML) is a group of neoplasms arising from precursor cells committed to the myeloid cell-line differentiation. "Decreased DUSP6 correlates to increased migration in PDAC and ATF3 regulates DUSP6 expression in secondary acute myeloid leukemia through direct binding of the Dusp6 gene." (PMID 41198649, 2025). "The regulatory role of ATF3 on metabolism was considered as a key driving factor for the aggressiveness of acute myeloid leukemia (AML)." (PMID 35052581, 2021). "In addition, the transcription factor ATF3 can maintain the biosynthesis of purines and pyrimidines and inhibit differentiation in acute myeloid leukemia (AML)." (PMID 35477416, 2022). "The epigenetic alteration results in its reduced expression level, and in turn increases the expression of SH3GL1 by reducing ATF3-mediated inhibition of SH3GL1, which is a fusion partner in acute myeloid leukemia and plays a role in leukemogenesis." (PMID 26169043, 2015).
COVID-19 (5 papers, 2021 to 2024). A disease caused by infection with severe acute respiratory syndrome coronavirus 2. "Early studies have confirmed that JUN, FOS, and ATF3 are up-regulated in COVID-19 patients and correlated with the severity of COVID-19." (PMID 36380355, 2022). "In agreement with previous studies, we also highlighted the elevation of ATF3, CEBPB, FOSL2, and MITF with COVID-19 severity." (PMID 39712003, 2024). "In the COVID-19 cohort, IL6, PTSG2, JUN, ATF3, SOCS3, CSF3, and NFKB2 had AUC values greater than 0.7." (PMID 36380355, 2022).
diabetic nephropathy (5 papers, 2018 to 2026). "Compared with the control (C57 or BKS), ATF3 expression was elevated in animal model of proteinuria (LPS-treated C57 mice) and the model of diabetic nephropathy (db/db mice)." (PMID 29038896, 2018). "For example, using the Raf inhibitor, GW5074 can reduce the excretion of ATF3 in urine and lower serum creatinine levels, indicating that the activation of ATF3 in diabetic nephropathy may be related to disease progression." (PMID 40461634, 2025). "Therefore, we believe that ATF3 is a new and effective biomarker for the diagnosis of early diabetic nephropathy." (PMID 34790229, 2021). "However, we show for the first time an induction of ATF3 in podocytes from patients with chronic kidney disease, including minimal change disease, focal segmental glomerulosclerosis, and diabetic nephropathy." (PMID 29038896, 2018). "To further test which glomerular cells have increased ATF3 expression in animal models, we examined the localization of ATF3 within the glomeruli in animal models of proteinuria, including the LPS model, a well-recognized proteinuric mouse model, and the db/db mouse of diabetic kidney disease." (PMID 29038896, 2018). "In summary, this study revealed an inducible ATF3 expression in podocyte injury induced by chronic disease, including minimal change disease (MCD), focal segmental glomerulosclerosis (FSGS), and diabetic nephropathy (DN)." (PMID 29038896, 2018). "The first finding is that there is an inducible ATF3 expression in podocytes from proteinuric patients with minimal change disease (MCD), focal segmental glomerulosclerosis (FSGS), and diabetic nephropathy (DN)." (PMID 29038896, 2018). "In this study, we found an inducible expression of ATF3 in glomerular podocytes from proteinuric patients with minimal change disease (MCD), focal segmental glomerulosclerosis (FSGS), and diabetic nephropathy (DN)." (PMID 29038896, 2018). "In contrast, ATF3 was increased in glomeruli from proteinuric patients with minimal change disease (MCD), focal segmental glomerulosclerosis (FSGS), and diabetic nephropathy (DN)." (PMID 29038896, 2018).
endometriosis (5 papers, 2020 to 2025). The growth of functional endometrial tissue in anatomic sites outside the uterine body. "This comparison revealed IL-33 and ATF3 as two significant regulators of ferroptosis in endometriosis." (PMID 37816731, 2023). "Hence, we aimed to test whether ATF3 participates in the IL-33-mediated upregulation of SLC7A11 in endometriosis." (PMID 37816731, 2023). "In endometriosis, IL-33/ST2 inhibits ATF3 by activating the p38/JNK signaling pathway, thereby upregulating the expression of SLC7A11, reducing ferroptosis, and protecting endometriotic stromal cells (eESCs) from damage." (PMID 41550926, 2025). "Moreover, macrophage-derived IL-33/ST2 has been shown to inhibit ferroptosis in endometriosis through the ATF3/SLC7A11 axis, indicating that macrophages may influence endometriosis ferroptosis via SLC regulation." (PMID 41150779, 2025).
epilepsy (5 papers, 2014 to 2021). A brain disorder characterized by episodes of abnormally increased neuronal discharge resulting in transient episodes of sensory or motor neurological dysfunction, or psychic dysfunction. "In general, ATF3's stimulatory role in regeneration is in accordance with other ATF3 functions such as providing neuroprotection in mouse epilepsy, ischaemia, neurotoxicity or ALS models." (PMID 27581653, 2016). "ATF-3 expression has been correlated with seizure frequency in epilepsy patients." (PMID 34301297, 2021). "In mouse ALS and epilepsy models, ATF3 overexpression resulted in reduced neurodegeneration." (PMID 27581653, 2016).
Hodgkins lymphoma (5 papers, 2008 to 2020). A heterogeneous group of malignant lymphoid neoplasms of B-cell origin characterized histologically by the presence of Hodgkin and Reed-Sternberg (HRS) cells in the vast majority of cases. "ATF3 expression was found to be elevated in several cancers such as breast cancer and Hodgkin lymphomas." (PMID 25149542, 2014). "ATF3 is also activated by serum stimulation and downstream of c-Myc, and is frequently over-expressed in various tumours including those of the prostate, breast, and Hodgkin's lymphomas." (PMID 22046379, 2011). "Additionally, ATF3 appears to be growth stimulatory in hepatocytes, dorsal root ganglion neurons, and classical Hodgkin lymphoma cells." (PMID 18808719, 2008). "In contrast to non-Hodgkin’s lymphoma and non-malignant tissue, a high level expression of ATF3 has been observed in Reed-Sternberg cells of patients with Hodgkin’s disease." (PMID 25872784, 2015).
kidney injury (5 papers, 2015 to 2024). Trauma to the kidney. "Another study also reported that miR494 binds to the 3′UTR of ATF3 to decrease the expression of ATF3, leading to adhesion molecule-induced kidney injury in the ischemia/reperfusion model." (PMID 38282657, 2024). "Like ATF3, HtrA3 proteins also play a protective role in ischemia–reperfusion kidney injury." (PMID 33462352, 2021).
lung adenocarcinoma (5 papers, 2014 to 2024). A carcinoma that arises from the lung and is characterized by the presence of malignant glandular epithelial cells. "The TCGA database confirmed that the levels of DDIT3 and ATF3 in Lung squamous cell carcinoma (LUSC) and lung adenocarcinoma (LUAD) tumor tissues were significantly decreased compared with normal tissues." (PMID 38244586, 2024).
renal fibrosis (5 papers, 2017 to 2026). A final common manifestation of a wide variety of chronic kidney diseases characterized by glomerulosclerosis and tubulointerstitial fibrosis. "In summary, ATF3 expression was induced by kidney fibrosis and ATF3 knockout alleviated renal fibrosis." (PMID 41522362, 2026). "And some of these proteins like CTSD, ATF3, Wnt5a were reported play important roles in renal fibrosis or other kidney disease." (PMID 28912732, 2017). "Taken together, our data shed light on the epigenetic side of renal fibrosis and provide evidence that the epigenetic interaction between ATF3 and HDAC6 might be a promising target for kidney fibrosis." (PMID 41522362, 2026). "Furthermore, out results suggested that TCONS_00088786 (neighbor of CtsD) and TCONS_01496394 (neighbor of ATF3) may be critically involved in renal fibrosis, with being regulated by TGF-β/Smad signaling, forming a feedback loop to regulate renal fibrosis." (PMID 28912732, 2017). "And some of these proteins like CTSD, ATF3, WNT5A were reported play important roles in renal fibrosis or other renal disease." (PMID 28912732, 2017).